PKD1L3 (polycystin 1 like 3, transient receptor potential channel interacting)
Description:
Pore-forming subunit of a heterotetrameric, non-selective cation channel that is permeable to Ca(2+). Also shows permeability towards NA(1+), K(+) and Mg(2+). Heterotetrameric complex channel is activated by external low pH and Ca(2+), but opens only when the extracellular pH rises again and after the removal of acid stimulus. May act as a sour taste receptor in gustatory cells; however, its contribution to sour taste perception is unclear in vivo and may be indirect.
Tractability: Antibody: UniProt places it where antibodies can reach, with high confidence; its Gene Ontology location is reachable by antibodies, with high confidence; UniProt predicts a signal peptide or a membrane-spanning region.
Gene: Protein-coding gene on chromosome 16 (71,929,538 to 72,000,402, reverse strand). Ensembl gene ENSG00000277481.
Subcellular location: Cell membrane
Gene Ontology:
Molecular function: pH-gated monoatomic ion channel activity; protein binding; calcium channel activity; calcium-activated cation channel activity; monoatomic cation channel activity; monoatomic cation transmembrane transporter activity; sour taste receptor activity
Biological process: calcium ion transmembrane transport; monoatomic cation transmembrane transport; sensory perception of sour taste; cellular response to acidic pH; detection of chemical stimulus involved in sensory perception of sour taste; detection of mechanical stimulus; monoatomic cation transport
Cellular component: extracellular exosome; plasma membrane; cation channel complex; cell surface; membrane; receptor complex
Genetic constraint (gnomAD): Loss-of-function variants: 207 observed, 170.32 expected, observed/expected ratio (o/e) 1.22, 90% interval 1.08 to 1.36. The synonymous counts are far from expectation, so gnomAD's model fits this gene poorly and the ratio says little. Missense variants: 2,459 observed, 2,012.5 expected, observed/expected ratio (o/e) 1.22, 90% interval 1.18 to 1.26. Synonymous variants: 930 observed, 763.29 expected, observed/expected ratio (o/e) 1.22, 90% interval 1.15 to 1.29.
Homologues: Orthologues: chimpanzee PKD1L3 (98% identical), macaque PKD1L3 (88% identical), dog PKD1L3 (61% identical), rat Pkd1l3 (58% identical), mouse Pkd1l3 (58% identical), rabbit PKD1L3 (55% identical), zebrafish pkd1l2a (30% identical), zebrafish pkd1l2b (25% identical), zebrafish pkd1a (18% identical), zebrafish pkd1b (14% identical), zebrafish pkd1l2b (8% identical), Drosophila melanogaster Pkd2 (5% identical), and 1 more. Paralogues in human: PKD1L2 (24% identical), PKD1 (17% identical), PKDREJ (16% identical), PKD1L1 (14% identical), LOXHD1 (9% identical), DENND5B (7% identical), DENND5A (7% identical), PKD2 (6% identical), PKD2L1 (6% identical), PKD2L2 (5% identical).
Diseases named in the same sentence as PKD1L3 in open-access papers:
PKD1L3 is named in the same sentence as 6 diseases in open-access papers, as found by Europe PMC text mining. Sharing a sentence is not in itself a finding about the gene and the disease. The quoted sentences say what the papers report.
polycystic kidney disease (4 papers, 2009 to 2021). A usually autosomal dominant and less frequently autosomal recessive genetic disorder characterized by the presence of numerous cysts in the kidneys leading to end-stage renal failure. "The heteromeric complex between PKD1L3, a member of the polycystic kidney disease (PKD) protein family, and PKD2L1, also known as TRPP2 or TRPP3, has been a prototype for mechanistic characterization of heterotetrametric TRP-like channels." (PMID 34381056, 2021). "The polycystic kidney disease-like ion channel PKD2L1 and its associatedpartner PKD1L3 are potential candidates for sour taste receptors." (PMID 21625513, 2011). "The following transcripts were undetectable in the patients, even after 50 cycles of amplification, but readily detectable in the sour-normal subjects: acid sensing ion channels (ASICs) 1a, 1β, 2a, 2b, and 3; and polycystic kidney disease (PKD) channels PKD1L3 and PKD2L1." (PMID 19812697, 2009). "Another mechanism assumes that two members of the polycystic kidney disease (PKD) family of channels, namely, PKD1L3 and PKD2L1, are involved at least in part." (PMID 19812697, 2009).
neuroblastoma (1 paper, 2015). Neuroblastoma (NB) is the most common solid, extracranial childhood tumor. "Among the neuroblastoma genes, RAD54B, BBS9 and UNKL were detected in exosomes while BBS9, IGFN1 and PKD1L3 were identified in ectosomes." (PMID 25944692, 2015).
polycystic kidney disease 2 (1 paper, 2021). Autosomal dominant polycystic kidney disease caused by a mutation in PKD2. "The polycystic kidney disease 1 and polycystic kidney disease 2–like proteins PKD2L1 and PKD1L3 have been identified as sour taste‐related receptors in human taste cells, and potential ion‐channel OTOP1 was present in taste cells in mouse that express Pkd2l1." (PMID 34401081, 2021).
kidney disease (3 papers, 2019 to 2023). "We found that polycystic kidney disease 1-like 3 (PKD1L3) and ubiquitin-specific peptidase 31 (USP31) were associated with FMDV-IRES activity." (PMID 35468926, 2022). "Proteins related to TRP channels, including TRP-melastatin 5 (TRPM5), polycystic kidney disease-1-like 3 (PKD1L3), and polycystic kidney disease-2-like 1 (PKD2L1), are also expressed in taste cells." (PMID 31040368, 2019).
infection (1 paper, 2024). The state of being infected such as from the introduction of a foreign agent such as serum, vaccine, antigenic substance or organism. "In contrast, the eomesodermin (EOMES) gene is overexpressed, and nucleoside diphosphate kinase A (NME1), polycystic kidney disease 1-like 3 (PKD1L3), as well as nanos homolog 1 (NANOS1) are down-regulated in the infection group." (PMID 38474155, 2024).
PKD1L3 also shares sentences with these, for which no sentence is quoted: cancer (1 paper).